MAST1 (microtubule associated serine/threonine kinase 1)
Diseases named in the same sentence as MAST1 in open-access papers (continued):
Sharing a sentence is not in itself a finding about the gene and the disease.
cancer (continued). "Later, the same group identified chaperone hsp90B as a binding partner and protein stabilizer of MAST1 in cancers." (PMID 35966591, 2022). "We further validated the correlation between USP1 and MAST1 protein in several cancer cell lines by Western blotting." (PMID 35966591, 2022). "Next, immunohistochemistry revealed that Hsp90β and MAST1 were highly expressed in cancer tissues of NSCLC patients." (PMID 36199626, 2022). "Considering the high expression of both USP1 and MAST1 in cancer tissues, we next used the Cancer Cell Line Encyclopedia (CCLE) database to analyze USP1-MAST1 correlation at mRNA level." (PMID 35966591, 2022). "It has been suggested that activation of MEK1 plays a vital regulatory role in MAST1-mediated chemotherapy resistance of cancer cells." (PMID 36199626, 2022). "The relative endogenous expression level of MAST1 is the main determinant in the development of cisplatin-resistance in various cancers; therefore, regulation of MAST1 protein abundance through the ubiquitin proteasomal system is critical." (PMID 35966591, 2022). "We found that both USP1 and MAST1 are more highly expressed in cancer than in normal tissue, and we confirmed this observation by immunohistochemistry using human tissue samples." (PMID 35966591, 2022). "The high scores of MAST1 mRNA corresponded with USP1 mRNA level across a wide range of cancer types." (PMID 35966591, 2022). "Evidence has been presented demonstrating that MAST1 has the biological function of promoting the cancer stem cell properties and radiation resistance." (PMID 36199626, 2022). "Collectively, these results clinically validate our findings and support the positive correlation of USP1 and MAST1 across different cancer types." (PMID 35966591, 2022). "Elevated MAST1 expression in cancers is one factor hampering the therapeutic success of cisplatin-based treatment." (PMID 35966591, 2022). "Accordingly, downregulated CHIP and upregulated Hsp90β and MAST1 were observed in cancer tissues from NSCLC patients and in NSCLC stem cells." (PMID 36199626, 2022). "The high expression of USP1 corresponded with MAST1 protein expression in the cancer cell lines we tested." (PMID 35966591, 2022). "The inhibition of hsp90 promotes E3 ligase CHIP-mediated ubiquitination of MAST1, resulting in cisplatin sensitization of cancer cells 12 and suggesting that MAST1 protein level is a key factor in circumventing cisplatin-resistance." (PMID 35966591, 2022). "In parallel, we performed genome-wide screening for DUBs that regulate MAST1 protein abundance in cancer cells." (PMID 35966591, 2022). "It is demonstrated that MAST1 rewires cRaf-Independent MEK activation to drive Cisplatin Resistance in Human Cancers." (PMID 36158685, 2022). "Given that MAST1 is a potential therapeutic target to battle cisplatin-resistance in cancers, our secondary screening aimed to identify DUBs that regulate MAST1 protein abundance." (PMID 35966591, 2022). "Our findings suggest that USP1 depletion destabilizes MAST1, which facilitates cisplatin sensitization in cancer." (PMID 35966591, 2022). "Collectively, these data indicate that cisplatin results in activation of GR and this activated GR binds to the GRE in the MAST1 promoter region to enhance transcription of MAST1 in cancer cells." (PMID 34400618, 2021). "On the contrary, knockdown of MAST1 abolished cisplatin-resistant cancer cell proliferation, tumor growth, and MEK-ERK phosphorylation obtained by enforced GR expression or activation in vitro and in vivo." (PMID 34400618, 2021). "In line with the changes seen in MAST1 mRNA, MAST1 protein level correlated with GR level in cisplatin-treated cancer cells." (PMID 34400618, 2021). "It is plausible that MAST1 is further activated or inhibited via its phospho-dynamics through cellular kinases or phosphatases in cancer cells." (PMID 34400618, 2021).
cancer (continued). "In conclusion, our study demonstrates that USP28 could enhance MAST1-driven cisplatin resistance by stabilizing MAST1 protein level in cancer." (PMID 38498222, 2024). "To develop a new strategy to overcome cisplatin resistance, we recently performed genome-wide screening for deubiquitinating enzymes (DUBs), and the results showed that DUBs promotes MAST1 protein stabilization by regulating its protein abundance in cisplatin-resistant cancer cells." (PMID 38498222, 2024). "MAST1 was also upregulated in 54% of cancer types (13 of 24)." (PMID 38498222, 2024). "Thus, the regulation of MAST1 protein level was considered as a critical factor for cisplatin resistance in cancer types." (PMID 38498222, 2024). "Furthermore, the expression level of USP28 corresponded with MAST1 protein in several tested cancer cell lines." (PMID 38498222, 2024). "Deciphering the molecular mechanism by which the ubiquitin proteasomal system regulates MAST1 protein turnover might be an effective way to advance MAST1-based therapy for cancer patients and overcome cisplatin-resistance." (PMID 35966591, 2022). "Thus, we examined the effect of targeting MAST1 with a small molecule inhibitor lestaurtinib on cisplatin re-sensitization in cancer cell lines and patient-derived tumor organoids treated with GR agonists." (PMID 34400618, 2021). "We also clinically validated our findings by demonstrating a correlation between the nuclear localization of GR and MAST1 expression levels as well as cisplatin resistance in primary tumor tissue samples collected from cancer patients before and after treatment with platinum-containing regimens." (PMID 34400618, 2021). "The MAST1 inhibitor, Lestaurtinib, was shown to block this cancer-promoting pathway." (PMID 34400619, 2021). "For instance, potential MAST1 interacting partners from the STRING database including membrane-associated guanylate kinase MAGI-2 or serine/threonine-protein phosphatase PPP2R2C/B could be alternative MAST1 regulators that drive cancer cisplatin resistance." (PMID 34400618, 2021). "Here, we delineate a unique molecular mechanism by which GR is activated by cisplatin and steroid, and how the activation of GR contributes to platinum resistance in human cancers through MAST1 using a series of preclinical studies and analysis of platinum-treated patient tumor specimens." (PMID 34400618, 2021). "Thus, we envision that inhibiting the regulation of MAST1 protein abundance by USP28 in cisplatin-resistant cancer cells may be effective alternative therapeutic strategy to overcome cisplatin resistance in cancer patients." (PMID 38498222, 2024). "Thus, USP28 may be a potential therapeutic target along with MAST1 to synergistically boost the effect of cisplatin-based treatment to overcome cisplatin resistance in cancer patients." (PMID 38498222, 2024). "Thus, we envision that the new targets regulating MAST1 protein abundance could help to reverse cisplatin-resistance in human cancers." (PMID 35966591, 2022). "MAST kinase stability is also likely regulated by ubiquitination, as MAST1 was also shown to be protected by ubiquitin-specific peptidases (USPs), USP1/USP28, and provided cisplatin resistance to cancer cells." (PMID 41237908, 2025). "The combination of pimozide and the MAST1 inhibitor lestaurtinib markedly decreases MAST1 expression and the phosphorylation of MEK1 and ERK in cancer cells, enhancing their sensitivity to cisplatin." (PMID 38702734, 2024). "MAST1 promotes pro-survival signaling by triggering MEK1 reactivation in a cRaf-independent manner, which produces cisplatin-resistance in human cancers." (PMID 35966591, 2022). "We further delineate the mechanism by which the depletion of USP1 downregulates MAST1-mediated activation of MEK1 and its downstream ERK1/2 in cancers." (PMID 35966591, 2022). "Cancer and adjacent normal tissues of NSCLC patients were collected to determine expression of CHIP, Hsp90β, and MAST1." (PMID 36199626, 2022).
cancer (continued). "Together, these findings suggest that Hsp90, MAST1 and USP1 may be excellent targets for cisplatin-resistant cancer cells, as their inhibition will enhance cisplatin sensitivity and result in increased cell death." (PMID 37569286, 2023). "Previous evidence has indicated that MAST1 may act as an activator of the MEK1 and MAPK cascade that in turn drives cisplatin resistance in human cancers." (PMID 36199626, 2022). "MAST1 was reported to induce cisplatin resistance in human cancers through rewiring MEK activation independent of cRaf." (PMID 36199626, 2022). "Overall, our results suggest that the pharmacological inhibition of both MAST1 and USP1 could mitigate cisplatin-resistance in cancerous tumors." (PMID 35966591, 2022). "Activation of MAST1 promoter was only observed in cancer cells treated with cisplatin, but not with other DNA damaging agents such as mitomycin C or camptothecin (CPT), demonstrating that the MAST1 induction occurs specifically through cisplatin." (PMID 34400618, 2021). "Indeed, active MAST1 circumvents cisplatin-mediated inhibition of the MAP kinase (MAPK) pathway and as such reactivates cancer cell growth." (PMID 34400619, 2021). "Dexamethasone, betamethasone, prednisolone, or triamcinolone restored cisplatin-resistant cancer cell survival and MEK-ERK phosphorylation, whereas treatment with the MAST1 inhibitor diminished the elevated MEK-ERK activity and cisplatin resistance in GR agonist-treated tumor cells." (PMID 34400618, 2021).
tumor (9 papers, 2013 to 2024). "Together, these results indicate that loss of USP28 decreased MAST1 protein level and suppressed tumor growth upon cisplatin treatment." (PMID 38498222, 2024). "Furthermore, we showed that the loss of USP28 downregulates MAST1 protein level and sensitizes cells for cisplatin toxicity during tumor growth, leading to reduced tumor size, volume and weight." (PMID 38498222, 2024). "Finally, loss of USP28 destabilized MAST1 protein and attenuated tumor growth by sensitizing cells to cisplatin treatment in mouse xenograft model." (PMID 38498222, 2024). "The combined targeting of USP1 and MAST1 by pimozide and lestaurtinib synergistically enhanced cisplatin sensitivity in the mouse xenografts, significantly reducing tumor volume and weight compared with a single treatment of pimozide or lestaurtinib." (PMID 35966591, 2022). "Altogether, our results showed that, upon cisplatin treatment, USP1-depletion downregulates MAST1 level and induces apoptosis that hampers tumor progression." (PMID 35966591, 2022). "To analyze the influence of USP1 on MAST1-mediated development of cisplatin-resistance during tumor progression, we performed several assays related to carcinogenesis." (PMID 35966591, 2022). "In this study, pharmacological inhibition of USP1 and MAST1 using pimozide and lestaurtinib synergistically boosted the effect of cisplatin toxicity on tumor growth." (PMID 35966591, 2022). "In this study, through multidisciplinary approaches, we identify a unique GR activation mechanism that is mediated by cisplatin and demonstrate how this activation contributes to cisplatin-resistant tumor growth through MAST1 induction." (PMID 34400618, 2021). "Co-treatment with dexamethasone and cisplatin restores cisplatin-resistant tumor growth, whereas addition of the MAST1 inhibitor lestaurtinib abrogates tumor growth while preserving the inhibitory effect of dexamethasone on inflammation in vivo." (PMID 34400618, 2021). "We determined that the circRNA of microtubule-associated serine/threonine kinase 1 (MAST1), or circMAST1, was significantly upregulated in HCC tissues and was closely related to tumor progression through a novel route." (PMID 32393764, 2020). "However, mice bearing USP28-depleted cells reconstituted with USP28 or MAST1 displayed increased tumor size, volume and weight." (PMID 38498222, 2024). "However, reconstitution with either USP1 or MAST1 resulted in significant increase in tumor volume and weight." (PMID 35966591, 2022). "In addition, lestaurtinib was identified as a promising MAST1 inhibitor that effectively sensitizes tumor cells to cisplatin in vitro and in vivo in patient-derived xenograft mouse models." (PMID 34400618, 2021). "Co-treatment with USP1 and MAST1 inhibitors abrogated tumor growth and synergistically enhanced cisplatin efficacy, suggesting a novel alternative combinatorial therapeutic strategy that could further improve MAST1-based therapy in patients with cisplatin-resistant tumors." (PMID 35966591, 2022). "MAST1 inhibitor lestaurtinib could diminish cisplatin-resistant tumor growth." (PMID 36199626, 2022). "In our study, we found that circMAST1 was derived from exons 9–11 of MAST1 located on chromosome 19p13.2 and that it was dramatically upregulated in HCC cell lines and tissues relative to non-tumor tissues." (PMID 32393764, 2020). "The overexpression of these MAST2 and MAST1 gene fusions displayed a proliferative effect; however, the function and (tumor) biology of the wildtype MAST proteins were not further investigated." (PMID 23717670, 2013). "Additionally, immunohistochemical staining of xenograft tumor tissues revealed reduced USP28 and MAST1 expression in the USP28-KO tumors compared with the mock control xenograft tumor tissues, while the expressions of USP28 and MAST1 were regained by reconstitution with USP28 or MAST1." (PMID 38498222, 2024).
tumor (continued). "Furthermore, the immunohistochemical analysis of the xenograft tumor tissues showed significantly reduced USP1 and MAST1 expression in the USP1KO tumors compared with the mock xenograft, and that expression was regained by reconstitution with USP1 or MAST1." (PMID 35966591, 2022). "Moreover, the interaction of Hsp90β with MAST1 could repress MAST1 ubiquitination at lysines 317 and 545 by CHIP and curbed proteasomal degradation; combined inhibition of Hsp90 and MAST1 could further disrupt MAST1 activity, which enhances cisplatin-triggered tumor growth arrest." (PMID 36199626, 2022).
neurodevelopmental disorder (1 paper, 2023). A behavioral and cognitive disorder with onset during the developmental period that involves impaired or aberrant development of intellectual, motor, or social functions. "MD-548 presents with the main clinical signs associated with the neurodevelopmental disorder caused by MAST1 mutations." (PMID 38003592, 2023).
MAST1 also shares sentences with these, for which no sentence is quoted: colon cancer (2 papers); cerebral palsy (1); cervical cancer (1); cognitive decline (1); Dyskinesia (1); Dystonia (1); esophageal cancer (1); Fibroadenoma (1); head and neck squamous cell carcinoma (1); hypogonadotropic hypogonadism (1); Intellectual disability (1); lung adenocarcinoma (1); malignant pheochromocytoma (1); microcephaly (1); neurological diseases (1); non-small cell lung carcinoma (1); paraganglioma (1); Tremor (1).